TMEM225B (transmembrane protein 225B)
Synonyms: GS1-259H13.2
Tractability: Antibody: UniProt predicts a signal peptide or a membrane-spanning region.
Gene: Protein-coding gene on chromosome 7 (99,597,868 to 99,611,045, forward strand). Ensembl gene ENSG00000244219.
Subcellular location: Membrane
Gene Ontology:
Molecular function: protein binding
Cellular component: membrane
Genetic constraint (gnomAD): Loss-of-function variants: 14 observed, 19.88 expected, observed/expected ratio (o/e) 0.7, 90% interval 0.46 to 1.1. The upper end of that interval is the gene's LOEUF score, 1.1, which puts it in group 4 of 6, group 1 being the genes least tolerant of losing a copy. Missense variants: 217 observed, 275.87 expected, observed/expected ratio (o/e) 0.79, 90% interval 0.7 to 0.88. Synonymous variants: 92 observed, 112.89 expected, observed/expected ratio (o/e) 0.81, 90% interval 0.69 to 0.97.
Homologues: Orthologues: chimpanzee TMEM225B (98% identical), macaque TMEM225B (92% identical), dog TMEM225B (74% identical), pig TMEM225B (63% identical).